RN7SKP151 (RN7SK pseudogene 151)
Gene: Miscellaneous RNA gene on chromosome 11 (13,353,208 to 13,353,523, forward strand). Ensembl gene ENSG00000222162.
Homologues: Orthologues: chimpanzee 7SK (96% identical). Paralogues in human: RN7SKP217 (74% identical), RN7SKP47 (73% identical), 7SK (73% identical), RN7SKP78 (72% identical), RN7SKP38 (72% identical), RN7SKP133 (72% identical), RN7SKP230 (72% identical), RN7SKP243 (72% identical), RN7SKP255 (72% identical), RN7SKP294 (72% identical), RN7SKP90 (72% identical), RN7SKP184 (71% identical), and 284 more.